ZNF593 (zinc finger protein 593)
Description:
Involved in pre-60S ribosomal particles maturation by promoting the nuclear export of the 60S ribosome. Negatively modulates the DNA binding activity of Oct-2 and therefore its transcriptional regulatory activity.
Synonyms: ZT86
Tractability: Small molecule: a structure with a bound ligand is known. PROTAC: ubiquitination databases record sites on it; its protein half-life has been measured.
Gene: Protein-coding gene on chromosome 1 (26,169,908 to 26,170,873, forward strand). Ensembl gene ENSG00000142684.
Subcellular location: Nucleus, nucleolus; Cytoplasm
Subcellular location (Human Protein Atlas): Nucleoli; Nucleoplasm
Gene Ontology:
Molecular function: preribosome binding; protein binding; zinc ion binding; nucleic acid binding; ribonucleoprotein complex binding
Biological process: negative regulation of RNA polymerase II regulatory region sequence-specific DNA binding; positive regulation of transcription by RNA polymerase II
Cellular component: nucleolus; nucleoplasm; cytoplasm; nucleus
Genetic constraint (gnomAD): Loss-of-function variants: 18 observed, 12.43 expected, observed/expected ratio (o/e) 1.45, 90% interval 0.99 to 1.9. The upper end of that interval is the gene's LOEUF score, 1.9, which puts it in group 6 of 6, group 1 being the genes least tolerant of losing a copy. Missense variants: 198 observed, 160.75 expected, observed/expected ratio (o/e) 1.23, 90% interval 1.1 to 1.39. Synonymous variants: 79 observed, 64.24 expected, observed/expected ratio (o/e) 1.23, 90% interval 1.02 to 1.48.
Homologues: Orthologues: chimpanzee ZNF593 (100% identical), macaque ZNF593 (96% identical), guinea pig ZNF593 (93% identical), pig ZNF593 (93% identical), mouse Zfp593 (90% identical), rabbit ZNF593 (90% identical), rat Zfp593 (89% identical), zebrafish znf593 (49% identical), tropical clawed frog znf593 (46% identical), Drosophila melanogaster CG3224 (43% identical), Caenorhabditis elegans znf-593 (33% identical). Paralogues in human: NDUFAB1 (21% identical).
Diseases named in the same sentence as ZNF593 in open-access papers:
ZNF593 is named in the same sentence as 2 diseases in open-access papers, as found by Europe PMC text mining. Sharing a sentence is not in itself a finding about the gene and the disease.
ZNF593 shares sentences with these, for which no sentence is quoted: infection (1 paper); type 2 diabetes (1).